IFNG (interferon gamma)
Diseases named in the same sentence as IFNG in open-access papers (continued):
Sharing a sentence is not in itself a finding about the gene and the disease.
Listeria infection (continued). "Notably, Listeria monocytogenes infection at ZT8 (afternoon) resulted in reduced bacterial spread and stronger inflammatory responses than infections at ZT0 (morning), a difference associated with higher levels of IL-1β, tumor necrosis factor-alpha (TNF-α), interferon-gamma (IFN-γ), and CCL2." (PMID 40585526, 2025). "While IL-12, IL-6 and IFNγ are all inducible by TNF, IL-18 is a cytokine upstream of TNF that has been described as playing a role in protection from Listeria infection." (PMID 29438281, 2018). "These cytokines are each well recognized to be essential for survival after Listeria infection through their role in coordinating activation of NK cells, NKT cell and T cells to produce IFNγ required for the bactericidal activity of phagocytic cells." (PMID 25599590, 2015). "In this work, we compared the requirement of IL-15 and IL-15Rα in controlling Listeria monocytogenes infection and determined that IL-15 signaling independent of IL-15Rα is critical for the induction of IFNγ and bacterial clearance." (PMID 34956227, 2021). "Blockage of STAT1 Ser phosphorylation, using STAT1 Ser mutants, significantly altered the IFNγ transcriptional response and its ability to clear Listeria monocytogenes infection, highlighting the relevance of STAT1 Ser phosphorylation in modulating IFNγ response in macrophages." (PMID 33357429, 2020). "Our previous study has demonstrated that SNX8 mediates IFNγ-triggered non-canonical signaling pathway and host defense against Listeria infection." (PMID 30321235, 2018). "Moreover, studies indicate that antigen-specific expansion of Tcm cells in elderly results in heightened production of interferon gamma (IFNγ) and tumor necrosis factor (TNF) compared to their adult counterparts, leading to improved survival rates in Listeria monocytogenes infection." (PMID 40740500, 2025). "Therefore, to further define a role for HOIL-1 in the innate immune system, we determined whether HOIL-1 KO bone marrow-derived macrophages (macrophages herein) produced cytokines in response to Listeria infection with or without IFNγ treatment." (PMID 25599590, 2015). "Indeed, a recent study demonstrated that IFNγ-unresponsive DCs failed to produce sufficient amount of IL-12, a key cytokine required for the development and function of Th1 cells during Listeria infection, which led to impaired immune responses against the pathogen." (PMID 25658840, 2015). "In agreement with our previous results, IFNγ production was not elicited in WT T cells within Alb∶Gag recipients, but could be induced in these same hosts when accompanied by inflammation during an acute Listeria infection." (PMID 25343644, 2014).
Splenomegaly (63 papers, 2007 to 2026). Abnormal increased size of the spleen. "Beyond body-weight loss and systemic IFNγ release, IL-18mutE2-treated animals also showed visible signs of systemic inflammation, including splenomegaly, hepatomegaly, hunched posture, ruffled fur, reduced food and water intake, and lethargy." (PMID 41488627, 2025). "We have tested the association of skin lesions, splenomegaly, hepatomegaly, and IFNγ and IgE levels in the serum to the Lmr loci on chromosomes 4, 11, 16, and 17 using AIL K3FV." (PMID 37600780, 2023). "The STS allele of these markers was responsible for lower level of IFNγ and IL-4 in serum, but with larger splenomegaly and larger skin lesions." (PMID 31231359, 2019). "Nonetheless, a Th1 immune response characterized by predominant IgG2 antibodies and higher IFNγ production seem rather associated with parasite control, as evidenced by a significant association with a reduced splenomegaly, and a tendency to lead to a decreased lesion size and duration." (PMID 25108307, 2014). "We tested the linkage to skin lesions, splenomegaly, hepatomegaly, and IFNγ and IgE levels in the serum." (PMID 37600780, 2023). "Linkage to splenomegaly was detected on chromosome 16 (Lmr18), whereas on chromosome 4 (Lmr24), only linkage to IFNγ level reached the significance threshold." (PMID 37600780, 2023). "In addition to more severe weight loss, splenomegaly, thrombocytopenia, hyperferritinaemia, and bone marrow hemophagocytosis, IL-18BP−/− mice also have significantly increased circulating IFNγ levels, further supporting a role for IL-18 in driving IFNγ release and ultimately MAS." (PMID 38566906, 2022). "During VL, splenomegaly is characterised by white pulp hyperplasia and IFNγ- and TNF-mediated killing of marginal zone macrophages, resulting in dysregulated lymphocyte trafficking." (PMID 33049000, 2020). "It was previously shown that it controlled hepatomegaly, splenomegaly, level of IgE and IFNγ in serum, and also infiltration of eosinophils to inguinal lymph nodes." (PMID 31231359, 2019). "Lmr24 on chromosome 4 influenced splenomegaly, levels of IFNγ, and IL-4 in serum and development of skin lesions." (PMID 31231359, 2019). "However, use of Ruxolitinib, a Janus Kinase (JAK) inhibitor, significantly reduced hypercytokinemia, splenomegaly, and death in an animal model of sHLH to a greater extent compared with administration of IFNγ monoclonal antibodies." (PMID 38566906, 2022). "Indeed, the absence of RELMα led to increased circulating inflammatory cytokines including TNFα, IFNγ, IL-6 and IL-1α, and exacerbated splenomegaly." (PMID 34349768, 2021). "Strikingly, despite uncontrolled hepatic parasite growth, as reported in IFNγ-deficient mice, mice lacking IFNγ receptor (IFNγR) showed no splenomegaly and complete preservation of MZM after 28 days of infection when MZM were lost in C57BL/6 controls." (PMID 26765224, 2016). "We observed a dramatic increase in the expression of several proinflammatory markers such as Il17a, Ifnγ, Tnfα, IL-1β and Ifitm1, and chemokines such as Ccl1, Cxcl10, Ccl22 and Xcl1, in ATMINΔLNBS1ΔL mice displaying splenomegaly, compared to the other genotypes." (PMID 26544571, 2015). "Our mRBC-aAPCs, comprised of membrane-bound 4-1BBL and IL-12, retained a favorable safety profile demonstrated by no significant changes in mice body weight and minimal, reversible changes in splenomegaly, liver inflammation, ALT elevations, and IFNγ levels." (PMID 33976146, 2021). "It inhibited the IFNγ-dependent Jak1/STAT1 signaling in LTo cells and endothelial cells within the spleen, thereby resulting in enhanced NF-κB signaling, increased proliferation of LTo and endothelial cells, and ultimately leading to splenomegaly." (PMID 39801977, 2025). "We also demonstrate that Irf5 expression in CD11c+ cells is essential for inducing splenomegaly, but it is not required for the development or maintenance of parasite-specific IFNγ-producing CD4 T cells." (PMID 32038622, 2019).
breast tumors (62 papers, 2007 to 2025). "In contrast, the growth rate of two independent MT/Shc2F/2F breast tumours was selectively impaired in mice that contain CD8+ T cells (CD8+/+) or retain intact interferon-γ (IFNγ) responses (IFNγ+/+) relative to their immune-deficient (CD8−/− and IFNγ−/−) counterparts." (PMID 28276425, 2017). "Lastly, elevated IFNγ levels were detected using a mAb-based tracer targeting IFNγ (89Zr-anti-IFNγ) in neu+ mouse breast tumours following treatment with HER2/neu DNA vaccines." (PMID 40265075, 2025). "Breast tumors presenting high expression of CD274 upregulated some ferroptosis drivers associated with prognosis: IDO1, IFNG and TNFAIP3." (PMID 38201582, 2023). "Expression of IFNG in breast tumor tissues was significantly increased in bulk samples of TCGA and GSE76250." (PMID 37154982, 2023). "Deletion of STUB1 in human prostate and breast tumour cells further sensitized them to growth inhibition induced by IFNγ." (PMID 35982220, 2022). "The mixture of recombinant human IFNγ (2 ng/ml, ~118 pM as a monomer) and the anti-IFNγ DNA aptamer (50–200 ng/ml) was added to the human breast tumor cell line in 10% fetal calf serum, and incubated at 37 °C for 10 min." (PMID 26690672, 2015). "In breast tumour cells, it has been postulated that the IFNγ induced anti-proliferative effects are reduced due to a lower sensitivity to SOCS3 induction." (PMID 20553623, 2010). "In breast tumors from the TCGA cohort, the expression of CD274 is associated with overall survival, and tumors presenting high expression levels of CD274 upregulated some ferroptosis-driver genes also associated with prognosis, like IDO1, IFNG and TNFAIP3." (PMID 38201582, 2023). "We examined whether IFNγ stimulation sensitized breast tumors to the cytotoxic effects of phenformin-induced ROS production." (PMID 34083537, 2021). "Interestingly, breast tumor-bearing mice on anti-CTLA4 therapy when placed on a low-salt diet demonstrated decreased peripheral circulatory levels of inflammatory cytokines (IFNγ and IL-1β) and reduced lung infiltrating of inflammatory immune cells along with reduced tumor progression." (PMID 40563574, 2025). "To identify which bacterial taxa within the breast tumor microbiome are associated with TILs, we quantified the abundance of CD8+ and FoxP3+ TILs and retrieved expression levels of genes indicative of CD8+ T cell activation from our prior data, including GZMA/B/K and IFNG." (PMID 39554133, 2024). "In the breast tumor transcriptome from the TCGA cohort, univariate overall survival analyses according to the expression of ferroptosis drivers highlighted a significant favorable expression for three of them: IFNG, IDO1 and TNFAIP3 conjointly with CD274 expression (univariate Cox p-value = 0.08)." (PMID 38201582, 2023). "The expression of CD274, IFNG, TNFAIP3 and IDO1 was investigated in an independent cohort of the transcriptome: METABRIC cohort comprising 1866 breast tumors." (PMID 38201582, 2023). "In a reported IL-12→27 sequence, the growth of immunogenic colon and breast tumors was suppressed through a CD4 and CD8 T cell and IFNγ-based anti-tumor response." (PMID 34209203, 2021). "Meanwhile, zinc nanoparticles loaded with porphyrin-lipid photosensitizer used for PDT in 4T1 breast tumors also reported an increase in serum TNF-α, IFNγ, and IL-2, one day after PDT." (PMID 36405502, 2021). "In breast tumour, just like its counterpart in the blood, the CCR6 defines an IL17A producer and the CD16 subtype is an IFNγ producer with high cytotoxic potential." (PMID 33268347, 2021). "Taken together, these data suggest that in the LUAD, LUSC and breast tumors, changes in the expression of NLRC5, CIITA, IFNG as well as hypermethylation may play a role in the repression of HLA." (PMID 39358601, 2024).
breast tumors (continued). "IFNγ production by peripheral NK cells from HCC patients in response to IL-12 and IL-18 was in keeping with that of another HCC cohort and by tumor-infiltrating NKs was similar to that seen in NK cells infiltrating breast tumors." (PMID 29867983, 2018). "Thus, we hypothesize that impairment of IFNγ signaling results in the suppression of T cell mediated immunity and CSC maintenance in breast tumors." (PMID 38831317, 2024). "We found that addition of TNFα, IFNγ, or TNFα + IFNγ did not significantly alter cell apoptosis or viabilities in cultured HUVECs, LLC cells, or tumour cells derived from MMTV-PyMT breast tumours." (PMID 34285232, 2021). "The breast tumour NCAM1-positive subtype that does not appear to have a counter part in the adult peripheral blood, is a strong IFNγ producer and higher expression of innate gene signature." (PMID 33268347, 2021). "The same was true for CIITA and IFNG in LUAD and LUSC tumors, but not ER+ breast tumors." (PMID 39358601, 2024).
emphysema (62 papers, 2004 to 2025). "This emphysema aggravation as a result of antibiotic exposure was associated with increased levels of inflammatory cells, IL-6, IFNγ and protein concentrations in bronchoalveolar lavage fluid." (PMID 37779147, 2023). "Increases in IFNγ- and IL-6-producing blood T cells to elastin fragments had a positive association with the annual rate of emphysema progression in active smokers." (PMID 34271910, 2021). "Inducible overexpression of IFNγ in lungs of mice caused emphysema with alterations in the balance of MMPs and antiproteases." (PMID 23533311, 2013). "In a study of mice exposed to cigarette smoke, a high fiber diet decreased interleukin-6 and interferon-gamma in bronchoalveolar lavage and serum samples, attenuated development of emphysema, and was protective against alveolar destruction." (PMID 38468283, 2024). "SCFA administration restored emphysema development with reduced inflammatory cells, IL-6, and IFNγ and decreased LC3B, atg3, and atg7 levels." (PMID 37779147, 2023). "Th1 cells are responsible for the production of interferon-gamma (IFN-γ), a probable cause of emphysema." (PMID 34418988, 2021). "Looking at lymphocytes, CD8 T-lymphocytes play an important role in inflammation and the development of emphysema by producing Interferon gamma (IFN- Υ), interferon-inducible protein-10 (IP-10) and monokine induced by interferon-gamma (MIG)." (PMID 29580274, 2018). "The areas under the receiver operating characteristic curve to predict emphysema for interferon gamma (IFN-γ), and interleukin 6 (IL-6) responses to EFs were 0.81 (95% CI of 0.74–0.88) and 0.79 (95% CI of 0.72–0.86) respectively." (PMID 22969766, 2012). "Both IL-18 and IFNγ have been reported to contribute to emphysema pathogenesis in mouse smoke, and increases in lymphoid aggregates are reported in mouse smoke models in a similar timeframe to emphysema progression." (PMID 28830544, 2017). "Overexpression of prototypical M1-inducer IFNγ may be able to induce emphysema, but so does overexpression of prototypical M2 induced IL-13." (PMID 23533311, 2013). "Oligoclonal expansion of CD4+ T cells in lung tissue of emphysema patients has been shown and immune responses against elastin as a component of lung tissue have been supported by increased production levels of IFNγ from peripheral blood CD4+ T cells in COPD patients." (PMID 34271910, 2021). "In response to interferon-inducible protein 10 and monokine induced by interferon, but not interferon gamma, lung macrophages secreted macrophage metalloelastase (matrix metalloproteinase-12), a potent elastin-degrading enzyme that causes tissue destruction and which has been linked to emphysema." (PMID 15526056, 2004). "It has been revealed that CV reduces emphysema in chronic obstructive pulmonary disease (COPD) and increases the anti-inflammatory cytokines and expression of the genes forkhead box P3 (FOXP3) and interferon gamma (IFNγ) in a model of asthmatic mice." (PMID 40298523, 2025). "Interferon-gamma (IFN-γ) and tumor necrosis factor-alpha (TNF-α) are the main proinflammatory cytokines contributing to Th1-driven inflammation, which often results in neutrophilic infiltration with mucus hypersecretion and tissue damage, eventually leading to chronic bronchitis and emphysema." (PMID 39063652, 2024). "However, they may also contribute to emphysema progression, particularly since the localised effects of IL-18 on tissue resident responder cells may be to increase IFNγ without the requirement for cognate antigen." (PMID 28830544, 2017).
cryptococcal infection (61 papers, 2009 to 2026). "These three intracellular cytokines were chosen for study due to their importance in host defenses against cryptococcosis (32, –, 35) and the loss of protection phenotype seen in vaccinated mice deficient in IFNγ, IFNγR, TNFα, or IL-23p19." (PMID 38980038, 2024). "We determined that vaccination with HK-fbp1 confers protective immunity against lethal Cryptococcosis in an interferon γ (IFNγ)-dependent manner." (PMID 39324785, 2024). "Numerous murine and human studies have revealed IFNγ and TNFα are essential for host defenses against cryptococcosis (34, 39, 50, –, 52)." (PMID 38980038, 2024). "GP vaccine-mediated protection against cryptococcosis was lost in IFNγ and IFNγ receptor knock-out mice." (PMID 38712080, 2024). "Deficiency in Batf3 cDC1 led to diminished CD4 accumulation and decreased IFNγ production across multiple organs, supporting that cDC1s are a major driver of potent Th1 responses during cryptococcal infection." (PMID 38349130, 2024). "We focused on IFNγ, tumor necrosis factor alpha (TNFα), and interleukin (IL)-23 as these three cytokines have known benefit in murine models of cryptococcosis (32, –, 36)." (PMID 38980038, 2024). "After cryptococcal infection, γδ T cells secrete IL-17A and interferon gamma (IFN-γ) in mature neutrophils." (PMID 37251371, 2023). "More importantly, as IFNγ is critical for protection against cryptococcal infection, we saw a cross-reactive IFNγ response to Cda proteins in ex vivo splenocyte stimulation assays." (PMID 36248898, 2022). "Striking effects of Th1-derived cytokines for immunity against cryptococcosis are noticed when genetically engineered C. neoformans strain H99 expressing IFNγ (H99-γ) was experimentally used in mice." (PMID 36177012, 2022). "The patient was diagnosed as interferon-gamma autoantibodies with disseminated cryptococcosis and Mycobacterium abscessus infection." (PMID 32188404, 2020). "During cryptococcal infection, stimulated lung-infiltrating T lymphocytes secrete both Th1 (IFNγ, IL-2) and Th2 (IL-4, IL-5, IL-10) cytokines." (PMID 29333430, 2017). "The importance of pro-inflammatory responses at the site of infection, and in particular IFNγ, for effective host immune responses to cryptococcal infection in HIV-infected patients has been reported." (PMID 25853653, 2015). "Moreover, peripheral blood mononuclear cells (PBMCs) obtained from subjects with a history of cryptococcosis have greater cryptococcal antigen-stimulated IFNγ production compared with PBMCs from healthy controls." (PMID 41440711, 2025). "The protective role of IFNγ in preventing disseminated cryptococcal infection is well established." (PMID 39807873, 2025). "Thus, our data add evidence to the indispensable role of IFNγ during cryptococcal infection and vaccination." (PMID 38712080, 2024). "It will be important to discern the effects of IFNγ on different brain-resident myeloid cells during cryptococcal infection in future studies, including how receptor expression and signalling patterns differ between tissue-resident and recruited inflammatory myeloid cells." (PMID 37938547, 2023). "The main protective cytokines produced during cryptococcal infections include IFNγ, IL-12 and IL-2." (PMID 29333430, 2017). "Interestingly, in response to IFNγ producing C. neoformans, IL 17A is secreted primarily from neutrophils in mice, and may be helpful in the clearance of cryptococcal infection." (PMID 25498576, 2015). "In experimental models of cryptococcosis using C. neoformans strain KN99, IFNγ is required for protection mediated by the cda123 and 4-Ag vaccines." (PMID 41440711, 2025). "Routine use of recombinant IFNγ therapy has not been recommended in guidelines but remains an alternative recommendation for patients with refractory cryptococcal infection." (PMID 29970809, 2018).
cryptococcal infection (continued). "Adult-onset immunodeficiencies, such as anti-interferon-gamma autoantibodies syndrome and anti-granulocyte-macrophage colony-stimulating factor (anti-GM-CSF) autoantibodies syndrome, have been recognized as a risk factor of non-HIV-associated cryptococcosis." (PMID 37754977, 2023). "Also, in patients with anti-IFNγ auto-antibodies with or without coinfections with NTM, cryptococcal infections are sometimes shown." (PMID 38203686, 2023). "However, one paper reported 10 non-HIV positive patients with cryptococcosis and disseminated NTM infection, in whom anti-IFNγ auto-antibodies were shown." (PMID 38203686, 2023).